BRCA2 (BRCA2 DNA repair associated)
Diseases named in the same sentence as BRCA2 in open-access papers (continued):
Sharing a sentence is not in itself a finding about the gene and the disease.
ovarian carcinoma (continued). "Elevated chromosome instability scores were observed in BRCA1-mutated samples over non-BRCA HRR-related mutations (P < 0.001), with BRCA2-mutated ovarian cancer exhibiting greater chromosome instability scores (P < 0.01)." (PMID 40687614, 2025). "Additionally, the cumulative risk of ovarian cancer by the age of 80 years is estimated to be 44% (95% confidence interval [CI]: 36–53%) for BRCA1 carriers and 17% (95% CI: 11–25%) for BRCA2 carriers." (PMID 40427158, 2025). "For instance, women who carry BRCA1 and BRCA2 gene mutations are at high risk of various cancers (e.g., breast, pancreas, and ovarian cancers) —but not everyone who inherits these mutations will develop cancer." (PMID 40832617, 2025). "Several mechanisms of PARPi resistance have been identified in vitro (e.g. cancer cell lines and patient-derived organoids) and in vivo (clinical samples) with significant differences based on genetic background (e.g. BRCA1 vs. BRCA2 mutant) and tumor types (e.g. breast vs. ovarian cancer)." (PMID 39927794, 2025). "Our study differs from the research conducted by Manchanda et al31 on the cost-effectiveness of population-based testing for BRCA1, BRCA2, RAD51C (OMIM 602774), RAD51D (OMIM 602954), BRIP1 (OMIM 605882), and PALB2 mutations for preventing breast and ovarian cancer in the following ways." (PMID 38353949, 2024). "Given the ineffectiveness of screening for ovarian cancer, prophylactic risk-reducing salpingo-oophorectomy (RRSO) is recommended between the ages of 35 and 40 for BRCA1 carriers and between the ages of 40 and 45 for BRCA2 carriers." (PMID 37864742, 2024). "Remarkably, although RTx-161 showed little to no activity as a single agent in PE01 ovarian cancer cells harboring a single BRCA2 mutant allele (BRCA2.5193 C > G), it strongly potentiated the effects of Olaparib and the combination was synergistic." (PMID 38580648, 2024). "Interestingly, BRCA2-null mouse ovarian cancer cells demonstrated a unique response to Wnt3A with the preferential upregulation of the Wnt signaling inhibitor Axin2." (PMID 39028933, 2024). "Ovarian cancer cells with mutations in BRCA1, BRCA2, or genes involved in the HR mechanism have an Homologous Recombination Deficiency (HRD) status, which renders them highly dependent on the DNA single-strand break (SSB) repair mechanism to maintain genomic stability." (PMID 39314634, 2024). "Hopefully, to possibly add another tool in helping to reduce the diagnostic time for patients with breast and/or ovarian cancer, our study brings new information about the most frequent mutations of BRCA1 and BRCA2 genes associated with breast or ovarian cancer in the Romania population." (PMID 38785549, 2024). "For ovarian cancer, the cumulative risk in carriers of BRCA1 PV is low under the age of 45 years but reaches more than 10% by the age of 55 years, whereas it remains low until the age of 65 years for BRCA2 mutation carriers." (PMID 38333895, 2024). "Likewise, among ovarian cancer patients free from selection biases, the rate of detection of variants in BRCA1/BRCA2 was roughly 20%, whereas the rate for MGP analysis ranged from 26% to 31%, corresponding to a 1.5-fold elevation." (PMID 38397209, 2024). "There were 1121 and 1275 female first-degree family members in BRCA1 and BRCA2 families, respectively, of whom 144 and 65 family members in BRCA1 families were diagnosed with breast and ovarian cancer, respectively, and the corresponding number in BRCA2 families were 152 and 19 (eTable 4)." (PMID 38333895, 2024). "In addition, decreased phosphorylation and enhanced stability of β-catenin were observed in BRCA2-null mouse ovarian cancer cells, which correlated with increased inhibitory phosphorylation on GSK3β." (PMID 39028933, 2024).
ovarian carcinoma (continued). "This has been demonstrated in ovarian cancer cells lines with BRCA1 mutations although 53BP1 does not mediate resistance in BRCA2 mutated cells." (PMID 39135999, 2024). "Key elements in the fight against ovarian cancer include access to molecular diagnostics, awareness of the presence of BRCA1 or BRCA2 gene mutations in the family, the use of effective treatment methods at an early stage of the disease, and improvement in the quality of comprehensive treatment." (PMID 38473394, 2024). "For breast and ovarian cancer risk assessment in the isolated populations of the Northern Isles of Orkney and Shetland (in Scotland, UK) and their diasporas, quantifying genetically drifted BRCA1 and BRCA2 pathogenic variants is important." (PMID 39438716, 2024). "In addition, patients with hereditary breast and ovarian cancers and P/LP variants in BRCA2 have been shown to have significantly lower AMH levels than controls, and 2 of our patients with P/LP variants in BRCA2 had low AMH (patients 1093 and 1985)." (PMID 39545410, 2024). "BRCA2 NM_000059.4:c.5576_5579delTTAA has been cited in breast and ovarian cancer cases." (PMID 39796670, 2024). "The most important genes associated with hereditary breast and ovarian cancers are BRCA1 and BRCA2." (PMID 38928478, 2024). "Besides, 9 out of 16 ovarian cancer cases (56.3%) harboured genetic variants: six BRCA1 (37.5%), two RAD51C (12.5%) and in one case BRCA2 (6.25%)." (PMID 39148954, 2024). "The first molecular investigation into the role of BRCA genes in breast and ovarian cancer within Romania was carried out in 2010, when 17 patients from unrelated hereditary breast and ovarian cancer families in northeastern Romania were screened for BRCA1 and BRCA2 mutations." (PMID 39272683, 2024). "Additionally, oral contraceptives have been reported to reduce ovarian cancer risk by 50–55% in BRCA1 mutation carriers and by 40% in BRCA2 mutation carriers." (PMID 39590130, 2024). "A review of published patient data from the United States, the United Kingdom, and Australia found that in ovarian cancer, the frequency of BRCA1 mutations in different countries ranged from 3.4% to 47%, and the frequency of BRCA2 mutations ranged from 1% to 12%." (PMID 38817903, 2024). "In addition to BRCA1 and BRCA2 mutations, it is crucial to recognize that various other genetic mutations, such as those in RAD51C, ATM, and CHEK2, can induce HR deficiency in ovarian cancer." (PMID 38391958, 2024). "Additionally, the BRCA2-mutant patients show a higher incidence of family history of ovarian cancer, resulting in a significant difference in the number of mutant patients with a family history of ovarian cancer." (PMID 38098088, 2023). "For example, BRCA1 and BRCA2 genes have been successfully targeted with poly (ADP-ribose) polymerase (PARP) inhibitors, leading to significant improvements in response rates and overall survival in patients with BRCA-mutated ovarian cancers." (PMID 37239452, 2023). "Poly (ADP-ribose) polymerase (PARP) inhibitors are one of the most successful examples of clinical translation of targeted therapies in medical oncology, and this has been demonstrated by their effective management of BRCA1/BRCA2 mutant cancers, most notably in breast and ovarian cancers." (PMID 37190285, 2023). "However, patients with BRCA1 mutations tend to have a higher risk of developing ovarian cancer by the age of 80; 44% (95% C.I, 36%-53%) for BRCA1 and 17% (95% C.I, 11%-25%) for BRCA2." (PMID 38017453, 2023).
ovarian carcinoma (continued). "Family history information was not available from the COG cohort and thus we could not determine if the patients who had germline variants in BRCA1, BRCA2, or PALB2 had a family history of breast or ovarian cancer." (PMID 38110397, 2023). "In addition, it has been described that BRCA2-mutant ovarian cancers with reduced CHD4 expression significantly correlate with shorter progression-free survival and shorter overall survival." (PMID 36672401, 2023). "Over the past thirty years, genetic testing for inherited pathogenic variants in the BRCA1 and BRCA2 genes in patients with suspected hereditary breast and ovarian cancer (HBOC) has moved from research to being an established part of breast and ovarian cancer care." (PMID 37563628, 2023). "Of the 30 ovarian carcinomas from the test cohort, 6 showed a mutation in BRCA1 and 5 in BRCA2." (PMID 38139296, 2023). "Since the study period, recommendations for genetic testing have evolved to include most women with ovarian cancer, mainstreaming of genetic testing, and inclusion of a test to detect germline pathogenic BRCA1 or BRCA2 genetic variants in the MBS from 2017, at a cost of ~$1,000 per eligible person." (PMID 37071628, 2023). "While germline BRCA1 or BRCA2 mutations have, until recently, been the only validated indications for PARPi-based therapy in breast and ovarian cancer, it has become clear that they were not the sole causes of an HRD phenotype." (PMID 37007122, 2023). "However, in BRCA2 wild-type cases of ovarian cancer, a high level of BRCA2 mRNA expression is one of the determinants of chemoresistance." (PMID 36899893, 2023). "While there are a few studies in the literature that explore hereditary ovarian cancer and gene mutations of BRCA1 and BRCA2, research specifically focusing on the prognostic factors of ovarian cancer has not been conducted in Cyprus." (PMID 38136256, 2023). "Unlike the small effect on the risk of breast and ovarian cancers, the BRCA2 p.K3326 mutation has shown to be associated with a remarkably increased risk of several other cancers." (PMID 37943872, 2023). "Oral hormonal contraception should not be negated in BRCA1/BRCA2 mutation carriers not yet eligible for risk-reducing surgery because it significantly reduces the risk of developing ovarian cancer." (PMID 36835955, 2023). "Indeed, it has to be underlined that, beyond breast and ovarian cancers, pathogenic variants in BRCA1 and BRCA2, as well as in CHEK2 and PALB2, have been associated with a higher risk of developing an increasing number of cancers." (PMID 35456488, 2022). "Other common indications include removal of gynecological cancers or risk reduction treatment in women with an inherited increased chance of ovarian cancer as due to gene mutations such as BRCA1, BRCA2 or HNPCC, or those with a strong family history of ovarian cancer." (PMID 35356299, 2022). "The approximate risk of ovarian cancer is 40% for BRCA1 PV and 20% in BRCA2 PV11,12." (PMID 35469032, 2022). "Finally, we identified common genetic variations in the CDK5RAP3 locus as potentially associated with breast and ovarian cancer risk in BRCA1 and BRCA2 mutation carriers." (PMID 35053516, 2022).
ovarian carcinoma (continued). "In addition to increased familial BC and ovarian cancer risk due to BRCA1 and BRCA2 germline mutations, approximately 40–45% of all hereditary BCs harbor BRCA1 germline mutations and 35–40% harbor BRCA2 germline mutations." (PMID 36140723, 2022). "However, multigene panel genetic testing for patients with breast and ovarian cancer now commonly includes DDR genes in addition to BRCA1 and BRCA2, a number of which are considered moderate or low-risk genes." (PMID 35626031, 2022). "We next analysed cervical samples from yet unaffected BRCA1 (n = 57) and BRCA2 (n = 53) mutation carriers (i.e. women who have not yet developed breast and/or ovarian cancer) and 114 healthy controls." (PMID 35105882, 2022). "Thus, our study demonstrates, for the first time, that ddPCR can be used for the accurate quantitation of BRCA1 and BRCA2 mRNA in FFPE ovarian cancer specimens." (PMID 35203410, 2022). "Consensus guidelines for hereditary breast and ovarian cancer include management recommendations for pathogenic/likely pathogenic (P/LP) variants in ATM, CHEK2, PALB2, and other DNA damage repair (DDR) genes beyond BRCA1 or BRCA2." (PMID 35626031, 2022). "There were 9 ovarian cancer patients with pathogenic variants and 10 with VUS in the BRCA2 gene." (PMID 35918668, 2022). "For ovarian cancer patients with optimal cytoreduction, combined expression of MAGEC3 and BRCA2 showed that patients that were BRCA2 expressors with MAGEC3 loss levels had better overall and progression-free survival compared with patients who were BRCA2 expressors with normal MAGEC3 levels." (PMID 36230652, 2022). "Somatic mutations in BRCA1 or BRCA2 genes are also occasionally present in sporadic (non-hereditary) ovarian cancers." (PMID 35203410, 2022). "The copy number gain of EMSY, which binds to BRCA2, exon 3, has been described in 17% of high-grade ovarian cancer, and it has been reported as an alternative mechanism for HRD, even if its role is controversial and it does not seem to confer sensitivity to PARPis." (PMID 36612041, 2022). "While ovarian cancers in BRCA1/2 carriers generally develop in the 4th or 5th decades of life, evidence suggests that risk of ovarian cancer begins to increase at age 35 for BRCA1 and age 40 for BRCA2." (PMID 35768821, 2022). "BRCA2 also emerged in our ovarian cancer-specific analysis (pLOF, p = 1.91 × 10−9)." (PMID 36199081, 2022). "BRCA1 and BRCA2 tumor analyses is done for all ovarian cancer patients." (PMID 35469032, 2022). "The most frequent SFs gene was BRCA2 (16 variants in 19 individuals), followed by BRCA1 (9 variants in 9 individuals), both of which were associated with increased susceptibility to breast and ovarian cancer." (PMID 36143288, 2022). "Finally, we identified common genetic variations in the CDK5RAP3 locus as potentially associated with breast and ovarian cancer risk in a large cohort of BRCA1 and BRCA2 mutation carriers." (PMID 35053516, 2022). "As expected, BRCA1 and BRCA2 PV rate nearly doubled in cases with a FH of PC nearly compared to sporadic subjects (3.6% vs. 1.7%), while it ranged from 1.7% to 15.8% in subjects with a personal or family history of breast/ovarian cancer." (PMID 36139606, 2022). "In our latest study, conducted among consecutive patients with ovarian cancer from the Podkarpacie region (South-Eastern Poland), we observed only 6.3% BRCA1 or BRCA2 founder mutation carriers, and a slightly different spectrum of these mutations than in other regions of Poland." (PMID 35382848, 2022). "Breast cancer susceptibility genes 1 and 2 (BRCA1 and BRCA2, OMIM #113705 and #600185, respectively) are the best known, most well established, and highly penetrant genes associated with increased risk of developing breast and ovarian cancers." (PMID 35456488, 2022). "The NCCN guidelines suggest the recommended age for RRSO is 35–40 years for BRCA1 mutations and 40–45 years for BRCA2 mutations, because there is no effective surveillance for ovarian cancer." (PMID 35191009, 2022).
ovarian carcinoma (continued). "The lifetime risk of breast and ovarian cancer is 45–80% in BRCA1 and BRCA2 mutation carriers." (PMID 35409996, 2022). "Besides breast and ovarian cancers, mutations of BRCA1 and BRCA2 genes also increase the risk of pancreatic and prostate cancers." (PMID 36010291, 2022). "Similarly, the lifetime risk of developing ovarian cancer is up to 44% for BRCA1 and 17% for BRCA2 variants." (PMID 35685436, 2022). "Pathogenic germline variants in these genes confer a high risk for developing breast and/or ovarian cancer that can reach 72% and 44% for BRCA1 mutation carriers and 69% (for breast cancer) and 17% (for ovarian cancer) for those with BRCA2 pathogenic alterations." (PMID 35898894, 2022). "Among the 10 recurrently found gBRCA1/2-PV (in more than 10 families) in the Japanese Organization Of Hereditary Breast and Ovarian Cancer (JOHBOC) registry in Japan, only three variants, BRCA1:c.2800C>T, BRCA2:c.6952C>T, and BRCA2:c.9076C>T, were identified in our OC cases." (PMID 35741847, 2022). "A high risk of malignant ovarian tumors is observed in women over the age of 49 with a burdened hereditary history (mutations of the BRCA1 and BRCA2 genes, Lynch syndrome, etc.)and after ovarian hyperstimulation, when using hormone replacement therapy, endometriosis, or obesity." (PMID 36359464, 2022). "In women who harbour a pathogenic or likely pathogenic variant in BRCA1 and BRCA2 screening for ovarian cancer is not recommended." (PMID 34565426, 2021). "Carriers of inherited pathogenic sequence variants (PSVs) in BRCA1 and BRCA2 are at an increased lifetime risk of developing ovarian cancer; recent reports highlighted that the cumulative risk of ovarian cancer to age 80 years was 44% for BRCA1 carriers and 17% (95% CI, 11-25%) for BRCA2 carriers." (PMID 34930165, 2021). "In the cancer cohort of 2,665 cases, we identified 74 BRCA pathogenic variants, 31 in BRCA1 with 40 carriers (2.1% in 1,880 cases) and 43 in BRCA2 with 61 carriers (2.5% in 2,417 cases), resulting in the prevalence of 3.8% in the Taiwanese cancer cohort of breast/ovarian cancer." (PMID 34235180, 2021). "A large genome-wide association study (GWAS) and meta-analysis of sporadic epithelial ovarian cancer cases, BRCA1 and BRCA2 carriers (15,252 and 8211 respectively) and 30,845 healthy controls identified genomic variants of Wnt pathway components, Wnt4 and RSPO1 genes, as new susceptibility loci." (PMID 34283069, 2021). "The primary objective of this study was to evaluate the BRCA mutation rate in families with PrC associated with breast and/or ovarian cancers; secondary aims were to compare the characteristics of families and BRCA-related PrC outcome among BRCA1 and BRCA2 carriers." (PMID 33710808, 2021). "This study estimated the prevalence of BRCA1 and BRCA2 PSVs among female patients ≥18 years of age that are diagnosed with ovarian cancer, peritoneal cancer, and fallopian tube cancer in the Gulf region, with the aim of informing clinical practice and improving clinical treatments in the future." (PMID 34930165, 2021). "The prevalence of ovarian cancer was lower among women with PVs in BRCA2 (9.1%, 723/7940)." (PMID 33926482, 2021). "The ratio of BRCA1 to BRCA2 mutations varies from population to population, but it is consistent with previous reports that germline BRCA1 mutation was more common than germline BRCA2 mutation in ovarian cancer cases." (PMID 34356066, 2021). "While these guidelines incorporate decades of evidence for BRCA1 and BRCA2, guidelines are not as clear for other, less well-characterized genes associated with increased ovarian cancer risk." (PMID 33926482, 2021). "One report showed an AGCT in both a BRCA1 and a BRCA2 series of ovarian cancers." (PMID 34069790, 2021).